PRKAR1B (protein kinase cAMP-dependent type I regulatory subunit beta)
Description:
Regulatory subunit of the cAMP-dependent protein kinases involved in cAMP signaling in cells.
Synonyms: MASNS; PRKAR1
Tractability: Small molecule: a structure with a bound ligand is known. Antibody: UniProt places it where antibodies can reach, with high confidence; its Gene Ontology location is reachable by antibodies, with medium confidence. PROTAC: ubiquitination databases record sites on it; its protein half-life has been measured.
Target class: Kinase; Protein kinase regulatory subunit; Enzyme
Gene: Protein-coding gene on chromosome 7 (549,196 to 728,268, reverse strand). Ensembl gene ENSG00000188191.
Subcellular location: Cell membrane
Pathways (Reactome):
Signal Transduction: DARPP-32 events; GPER1 signaling; Hedgehog 'off' state; PKA activation
Disease: ADORA2B mediated anti-inflammatory cytokines production; FCGR3A-mediated IL10 synthesis
Metabolism: Glucagon-like Peptide-1 (GLP1) regulates insulin secretion; PKA activation in glucagon signalling
Cellular responses to stimuli: High laminar flow shear stress activates signaling by PIEZO1 and PECAM1:CDH5:KDR in endothelial cells
Hemostasis: Factors involved in megakaryocyte development and platelet production
Neuronal System: CREB1 phosphorylation through the activation of Adenylate Cyclase
Transport of small molecules: Vasopressin regulates renal water homeostasis via Aquaporins
Gene Ontology:
Molecular function: cAMP-dependent protein kinase inhibitor activity; cAMP-dependent protein kinase regulator activity; protein binding; protein kinase A catalytic subunit binding; cAMP binding
Biological process: negative regulation of cAMP/PKA signal transduction; activation of protein kinase A activity; adenylate cyclase-activating G protein-coupled receptor signaling pathway; cellular response to glucagon stimulus; chemical synaptic transmission; negative regulation of inflammatory response to antigenic stimulus; renal water homeostasis; vascular endothelial cell response to laminar fluid shear stress; modulation of chemical synaptic transmission; positive regulation of excitatory postsynaptic potential; positive regulation of fear response; positive regulation of long-term synaptic potentiation; regulation of synaptic vesicle cycle
Cellular component: cytoplasm; plasma membrane; cAMP-dependent protein kinase complex; ciliary base; cytosol; glutamatergic synapse; hippocampal mossy fiber to CA3 synapse; multivesicular body; postsynapse; Schaffer collateral - CA1 synapse; synapse
Genetic constraint (gnomAD): Loss-of-function variants: 22 observed, 45.81 expected, observed/expected ratio (o/e) 0.48, 90% interval 0.34 to 0.69. The upper end of that interval is the gene's LOEUF score, 0.69, which puts it in group 2 of 6, group 1 being the genes least tolerant of losing a copy. Missense variants: 445 observed, 533.53 expected, observed/expected ratio (o/e) 0.83, 90% interval 0.77 to 0.9. Synonymous variants: 259 observed, 221.57 expected, observed/expected ratio (o/e) 1.17, 90% interval 1.05 to 1.3.
Homologues: Orthologues: chimpanzee PRKAR1B (99% identical), guinea pig PRKAR1B (97% identical), mouse Prkar1b (95% identical), rat Prkar1b (95% identical), dog PRKAR1B (94% identical), pig PRKAR1B (93% identical), zebrafish prkar1b (92% identical), tropical clawed frog prkar1b (92% identical), macaque PRKAR1B (75% identical), Drosophila melanogaster Pka-R1 (67% identical), Caenorhabditis elegans kin-2 (56% identical). Paralogues in human: PRKAR1A (81% identical), PRKAR2B (40% identical), PRKAR2A (39% identical), CNBD1 (18% identical).
Diseases named in the same sentence as PRKAR1B in open-access papers:
PRKAR1B is named in the same sentence as 37 diseases in open-access papers, as found by Europe PMC text mining. Sharing a sentence is not in itself a finding about the gene and the disease. The quoted sentences say what the papers report.
Cognitive impairment (3 papers, 2021 to 2025). Abnormal cognition is characterized by deficits in thinking, reasoning, or remembering. "We speculate that Prkar1b, Prkacb and GluR3, commonly downregulated in both restraint stress and in a model of TNBC, may be novel drug targets to enhance cognitive impairment caused by the stress and anxiety of a cancer diagnosis." (PMID 40172096, 2025). "However, variants of genes that are enriched or specifically expressed in brain tissues, such as PRKACB or PRKAR1B, appear to produce more cognitive deficits, as is the case with MASNS." (PMID 38481146, 2024). "We propose a PRKAR1B-associated NDD with GDD, ASD, neurologic anomalies, and cognitive impairment (no formal IQ scores have yet been obtained from the reported individuals) as principal features." (PMID 33833410, 2021).
Intellectual disability (3 papers, 2021 to 2025). "It is suggested that PRKAR1B haploinsufficiency is the primary mechanism underlying the intellectual disability phenotype for 7p22.3 deletion." (PMID 40747102, 2025). "We characterize the clinical and molecular phenotypes of six unrelated individuals with intellectual disability and autism spectrum disorder who carry heterozygous missense variants of the PRKAR1B gene, which encodes the R1β subunit of the cyclic AMP-dependent protein kinase A (PKA)." (PMID 33833410, 2021). "The haploinsufficiency of the PRKAR1B gene due to the 7p22.3 deletion and the absence of pathogenic mutations in other genes within this deletion is the (primary) causative factor for the intellectual disability phenotype observed in our patient." (PMID 39152504, 2024).
Marbach-Schaaf neurodevelopmental syndrome (3 papers, 2024 to 2025). "Neurological abnormalities such as developmental delay, hypotonia and apraxia/dyspraxia found in our patient may be described by the recently identified Marbach-Schaaf Neurodevelopmental Syndrome (MASNS) associated with the PRKAR1B gene." (PMID 39152504, 2024). "Marbach-Schaaf neurodevelopmental syndrome (MASNS) is an ultra-rare, monogenic disease caused by pathogenic variation in PRKAR1B, which codes for the R1β regulatory subunit of protein kinase A (PKA), a key effector of cAMP signaling within the nervous system." (PMID 41163438, 2025). "Among the genes affected by our 7p22.3 deletion, PRKAR1B is of particular interest due to its established autosomal dominant inheritance pattern in Marbach-Schaaf neurodevelopmental syndrome." (PMID 40747102, 2025).
Anxiety (2 papers, 2021 to 2025). Intense feelings of nervousness, tension, or panic often arise in response to interpersonal stresses. "In the open-field test, Prkar1b-deficient rats exhibited increased durations of vertical activity and time spent in the center of the arena, suggesting that they required more time to acquire spatial knowledge and/or felt less fear or anxiety." (PMID 33479380, 2021).
breast carcinoma (2 papers, 2011 to 2021). "PKA and PP1 subunit mRNA expression was also assessed; PPP1CA, PRKACG and PRKAR1B were associated with breast cancer–specific survival." (PMID 33991172, 2021). "Our findings suggest that PPP1CA, PRKACG and PRKAR1B are associated with breast cancer–specific survival." (PMID 33991172, 2021). "PKA and PP1 subunit mRNA was also assessed; PPP1CA, PRKACG and PRKAR1B were associated with breast cancer–specific survival." (PMID 33991172, 2021). "PRKACG, PRKAR1B and PPP1CA were the most strongly and reproducibly associated with breast cancer–specific survival." (PMID 33991172, 2021).
Adrenal insufficiency (1 paper, 2025). Insufficient production of steroid hormones (primarily cortisol) by the adrenal glands. "Therefore, the potential down-regulation of Bcl2 mentioned earlier, and the potential up-regulation of Prkar1b in the PNS cows could indicate increased apoptosis within the adrenal cortex, as well as adrenal insufficiency caused by decreased PKA activity." (PMID 40004522, 2025).
Alzheimer disease (1 paper, 2024). A progressive, neurodegenerative disease characterized by loss of function and death of nerve cells in several areas of the brain leading to loss of cognitive function such as memory and language. "A subsequent genetic study of the PRKAR1B gene identified 7 variants in FTD and Alzheimer’s disease (AD) patients but these were not predicted to be pathogenic." (PMID 38481146, 2024).
epilepsy (1 paper, 2024). A brain disorder characterized by episodes of abnormally increased neuronal discharge resulting in transient episodes of sensory or motor neurological dysfunction, or psychic dysfunction. "The question of whether the deficiency of the PRKAR1B gene is directly involved in the development of an epilepsy remains open, as there is little evidence for this association." (PMID 39152504, 2024).
fibrosarcoma (1 paper, 2025). A malignant mesenchymal fibroblastic neoplasm affecting the soft tissue and bone. "A congenital fibrosarcoma with PRKAR1B::BRAF fusion was found by histological analysis: PRKAR1B encodes a regular subunit of the cyclin AMP-dependent protein kinase A complex, implicated in neurodegenerative dementia but not well associated with cancer, while B-RAF is a well-known proto-oncogene." (PMID 41245797, 2025).
Iron deficiency (1 paper, 2019). "Iron deficiency altered methylation at the genes regulating ephrin B signaling/ephrin receptor signaling (data not shown), including increased methylation at Ephb1, Itsn1, Prkar1b, and Srgap2, and decreased methylation at Arhgef15, Mknk1, and Slit3 loci." (PMID 31137889, 2019).
meningioma (1 paper, 2019). A generally slow growing tumor attached to the dura mater. "Next, a database reporting the expression level of different genes in 68 meningioma cases was interrogated with BioGPS to explore the relationship between PRKACA gene, coding for PKA CAT, and PKA regulatory subunits (PRKAR1A, PRKAR1B, PRKAR2A, and PRKAR2B) gene products." (PMID 31671850, 2019).
neuroblastoma (1 paper, 2022). Neuroblastoma (NB) is the most common solid, extracranial childhood tumor. "We also used the neuroblastoma SHSY5Y cell line to confirm our findings: both genes were significantly downregulated in the demethylated neuroblastoma cell line as well (PRKAR1B p = 6.33 × 10−05, HEATR2 3.37 × 10−06)." (PMID 35578268, 2022).
pulmonary diseases (1 paper, 2018). "PRKAR1B has shown to be implicated in neurodegenerative disorders, however, a role for PRKAR1B in pulmonary diseases is currently unknown." (PMID 30390659, 2018).
sarcoma (1 paper, 2022). A usually aggressive malignant neoplasm of the soft tissue or bone. "Through such method, genes highly associated with sarcoma subtypes, such as PRKAR1B, INPP5A, GLI3, and other genes, were obtained." (PMID 36619306, 2022). "The specific expression of genes obtained from the annotation of highly correlated methylation site features, such as PRKAR1B, INPP5A, and GLI3, was proven to be associated with sarcoma by publications." (PMID 36619306, 2022). "At present, few studies have been conducted on the role of PRKAR1B gene in sarcoma, but it has been reported to play an important role in various tumors." (PMID 36619306, 2022). "Therefore, the methylation of PRKAR1B gene may be very important for the identification or tumorigenesis of sarcoma, which deserve further investigation." (PMID 36619306, 2022).
Tremor (1 paper, 2021). An unintentional, oscillating to-and-fro muscle movement about a joint axis. "We demonstrated that Prkar1b-deficient rats exhibited tremor and abnormal behaviors associated with hippocampal functions." (PMID 33479380, 2021). "In the present study, we revealed that deficiency of the Prkar1b gene was causative of tremor in rats." (PMID 33479380, 2021). "Prkar1b-deficient rats exhibited spontaneous tremor after weaning, particularly during walking and rearing, and the tremor was evident on the lateral sides of the trunk." (PMID 33479380, 2021). "Thus, we concluded that the loss of function of the Prkar1b gene was causative of the tremor phenotype in rats." (PMID 33479380, 2021). "Thus, we consider that the PRKAR1B protein is reduced in both mutants, thus causing the tremor phenotype." (PMID 33479380, 2021).
cancer (9 papers, 2011 to 2026). A tumor composed of atypical neoplastic, often pleomorphic cells that invade other tissues. "In this study, significant differences in PRKAR1B expression were observed across various cancer types." (PMID 41798949, 2026). "This included positive associations between losses in 1p36.32, 3p26.2, 4q35.2, 7p22.3 and 18q23 with the expression of the cancer-related genes CDKN11B, CRBN, IRF2, PRKAR1B and NFATC." (PMID 33945543, 2021). "Among these, LAMA2, DUSP1, PRKAR1B, and APP were downregulated while the rest of the genes were upregulated in cancer as compared to normal cervical samples in the samples used for microarray." (PMID 24403257, 2013).
neurodevelopmental disorder (4 papers, 2021 to 2025). A behavioral and cognitive disorder with onset during the developmental period that involves impaired or aberrant development of intellectual, motor, or social functions. "We now report six unrelated individuals with variants of PRKAR1B, who share similar features indicative of a neurodevelopmental disorder." (PMID 33833410, 2021). "Prkar1b is a regulatory subunit of cyclic AMP-dependent protein kinase (PKA) and is associated with neurodevelopmental disorders and neurodegeneration in general including distinctions among symptomatic and asymptomatic forms of AD." (PMID 40979532, 2025). "Our study provides strong evidence for a PRKAR1B-related neurodevelopmental disorder." (PMID 33833410, 2021).
neurodegenerative disease (3 papers, 2022 to 2025). A disorder of the central nervous system characterized by gradual and progressive loss of neural tissue and neurologic function. "While the incorporation of different R‐subunits is linked to various maladies, only mutations in the PRKAR1B gene, encoding for the RIβ‐subunit, are linked with neurodevelopmental or neurodegenerative diseases." (PMID 40244081, 2025). "We characterized a novel neurodegenerative disease, neuronal loss, and parkinsonism driven by PRKAR1B mutation (NLPD‐PKA), demonstrating disrupted holoenzyme assembly, reduced cooperativity, and increased catalytic subunit nuclear translocation, altering gene expression in patient‐derived cells." (PMID 40244081, 2025).
brain disease (1 paper, 2015). "Moreover, 10 genes (ATP1A1, ATP6V1D, C16orf45, CROCC, KLC1, LUC7L2, PIAS2, PRKAR1B, RBFOX1, and RPL19) interacts with at least one brain disease-associated gene." (PMID 26043779, 2015).
PRKAR1B also shares sentences with these, for which no sentence is quoted: tumor (6 papers); apraxia (2); autism (1); autism spectrum disorder (1); cervical cancer (1); colitis (1); cystic fibrosis (1); developmental delay (1); fibroblastic disorder (1); head and neck squamous cell carcinoma (1); lung fibrosis (1); lymphoma (1); memory impairment (1); neurological disorders (1); osteosarcoma (1); Parkinsonism (1); prostate carcinoma (1); renal cell cancer (1).